TRPV3 (transient receptor potential cation channel subfamily V member 3)
Diseases named in the same sentence as TRPV3 in open-access papers (continued):
Sharing a sentence is not in itself a finding about the gene and the disease.
atopic dermatitis (15 papers, 2017 to 2026). "In addition to hereditary Olmsted syndrome pruritus, TRPV3 is closely associated with the development and progression of various skin diseases since it is significantly increased in the epidermal cells of patients with acquired skin diseases such as rosacea, psoriasis and atopic dermatitis." (PMID 36677834, 2023). "In summary, although TRPV2 was downregulated in pruritic skin regions of psoriasis and phymatous rosacea and TRPV3 was downregulated in skin biopsies from patients with atopic dermatitis, TRP channels appear to be upregulated in most skin disease studies." (PMID 36552866, 2022). "In other studies, osthole inhibited atopic dermatitis chronic itch by directly downregulating TSLP production from keratinocytes or activating warm-temperature Ca2+-permeable TRPV3 channels." (PMID 34691215, 2021). "A TRPV3 inhibitor that can effectively relieve atopic dermatitis when applied topically." (PMID 36677834, 2023). "Additionally, TRPV3 upregulation has been observed in mouse models of atopic dermatitis (AD) and inhibition of TRPV3 channel activity has shown promise in attenuating AD symptoms." (PMID 37629111, 2023). "Indeed, TRPV3 protein levels were increased in skin biopsies of several chronic itch diseases such as atopic dermatitis, rosacea, and psoriasis." (PMID 37474531, 2023). "While one study found increased TRPV3 expression in both lesional atopic dermatitis and lesional psoriasis skin when compared to healthy controls, another study examining the itch transcriptome of eczema and psoriasis found increased TRPV3 gene expression in pruritic psoriatic skin only." (PMID 36613861, 2022). "According to our experimental results, topical fluoxetine reduced TRPV3-driven inflammation and pruritus with an efficacy comparable to that of dexamethasone, suggesting that fluoxetine could be used as a steroid-sparing agent for conditions such as atopic dermatitis." (PMID 40699677, 2025). "The link between TRPV3 and protease-activated receptor 2 (PAR2) was found in conditions of atopic dermatitis." (PMID 37239947, 2023). "In contrast, in skin biopsies from patients with atopic dermatitis, TRPV1 and TRPV2 were upregulated and TRPV3 and TRPM8 were downregulated." (PMID 36552866, 2022). "Administration of scutellarein in mice suppressed atopic dermatitis induced by 2,4-dinitrofluorobenzene and pruritus induced by carvacrol and alleviated epidermal hyperplasia and skin inflammatory response, but showed no benefit in TRPV3-knockout mice in the carvacrol model." (PMID 37239947, 2023).
psoriasis (10 papers, 2016 to 2026). An autoimmune condition characterized by red, well-delineated plaques with silvery scales that are usually on the extensor surfaces and scalp. "An elevated expression of TRPV3 is also linked to atopic dermatitis and psoriasis, inflammatory skin conditions, in which TRPV3 activation might contribute to chronic pruritus." (PMID 41118703, 2025). "Overexpression, gain of function, and activation of channels, including nAChR, TRPV1, TRPV3, TRPV4, TRPM4, and ANO1 in keratinocytes, as well as TRPV1, nAChR, Kv1.3, and KCa3.1 in immune cells, have been associated with the induction of psoriasis." (PMID 38474002, 2024). "Aberrant expression of TRPV1 is implicated in multiple pain associated conditions including diabetic neuropathy, irritable bowel syndrome, chronic pancreatitis, vulvodynia, and TRPV3 is elevated in inflammatory skin-related conditions like psoriasis." (PMID 33671852, 2021). "Interestingly, a recent preliminary report describes a mechanistic link between TRPV3 activity in psoriasis through IL-1α and EGFR signalling." (PMID 27618069, 2016). "Several studies have reported alterations in TRPV3 mRNA and/or protein expression in pathological states, including in the skin of burns victims; in rosacea, a chronic inflammatory skin condition; in psoriasis and in breast tissue biopsies from patients with breast pain." (PMID 27618069, 2016). "Growing evidence suggests the involvement of multiple TRP subtypes in the pathogenesis of psoriasis, including altered expression of vanilloid subtypes, such as TRPV1, TRPV3, TRPV4, TRPV6, the canonical TRPC6, and melastatin TRPM8 in patients." (PMID 41689746, 2026). "Specifically, peripheral blood mononuclear cells from individuals with psoriasis exhibit elevated expression of TRP channels such as TRPM2 and TRPV1 and decreased expression of TRPM4, TRPM7, TRPV3, TRPV4, and TRPC6." (PMID 38474002, 2024). "Analysis of skin biopsies revealed that TRPV2 was downregulated in itchy skin regions of psoriasis patients, while FAAH1, TRPV1 and TRPV3 were upregulated." (PMID 36552866, 2022).
inflammatory skin disease (8 papers, 2017 to 2025). Inflammatory skin disorders covers a broad category that includes many conditions ranging in severity, from mild itching to grave medical health complications These disorders are common in people of all ages and races. "As a multimodal sensory channel, TRPV3 is abundantly expressed in keratinocytes and implicated in inflammatory skin disorders, itch, hair morphogenesis, and pain sensation." (PMID 33876725, 2021). "Overactive TRPV3 channels contribute to numerous inflammatory skin diseases, and this highlights the therapeutic potential of its inhibitors." (PMID 40699677, 2025). "It decreased the calcium concentration in cytosol in NHEK and HEK293T cells with overexpression of hTRPV3 and inhibited the release of IL-6 and IL-8 via TRPV3 in keratinocytes, which indicates that it can be used in phytotherapy of inflammatory skin diseases." (PMID 40943669, 2025). "Recently, investigations into ion channels, such as Orai-1, TRPV1, and TRPV3, have shed new light on potential targets for the treatment of inflammatory skin diseases, such as AD." (PMID 29348776, 2017). "Overall, further identification of drugs targeting the TRPV3 channel may provide effective treatment options for skin inflammatory diseases." (PMID 40699677, 2025). "It has been established that TRPV3, which is abundantly expressed in keratinocytes, is involved in the maintenance and functioning of the skin barrier and mediates the development of inflammatory skin diseases, wound healing, the transmission of pain signals, and hair morphogenesis." (PMID 37239947, 2023). "Recent research indicates that TRPV3 also plays a critical role in inflammatory skin diseases." (PMID 37239947, 2023).
migraine (8 papers, 2013 to 2024). "TRPV3 rs7217270 was associated with increased migraine risk based on the dominant model (AA + AG vs. GG: ORadj = 1.63, 95% CI = 1.02–2.58, p = 0.039)." (PMID 37303955, 2023). "A recent study investigating single nucleotide polymorphisms among the Spanish population identified the TRPV1 and TRPV3 genes as likely candidates for contributing to an increased genetic susceptibility to migraine." (PMID 26109436, 2015). "The present study showed that TRPV1 rs8065080, TRPV3 rs7217270, and TRPM8 rs17862920 were significantly associated with migraine or MO risk." (PMID 37303955, 2023). "Associations between SLC17A8, SHANK1, TRPV1, TRPV3 and TRPM8 gene polymorphisms and the risk of migraine by aura." (PMID 37303955, 2023). "Single nucleotide polymorphisms associated with the susceptibility for migraine have been identified in genes coding for TRPV1 and TRPV3 but the pathophysiological relations with known migraine mechanisms are yet unclear." (PMID 31948011, 2020). "Several SNPs in TRPV1, TRPV3, and TRPM8 were found to be associated with migraine susceptibility in meta-analyses of observational studies and GWAS." (PMID 33193064, 2020). "Consistent results were obtained for TRPV3 rs7217270 in the Migraine with aura group and TRPV1 rs222741 in the overall migraine group, suggesting the involvement of the vanilloid TRPV subfamily of receptors to the genetic susceptibility to migraine." (PMID 23815568, 2013). "Recent studies have highlighted a potential role for new genes, like MTHFR, KCNK18, TRPV1, TRPV3, and new neurotransmission systems, like the hypocretin system, both in migraine and cluster headache." (PMID 23848401, 2013). "Associations between the GRIK2, TRPV1, TRPV3 and TRPM8 gene polymorphisms and the risk of migraine." (PMID 37303955, 2023).
lung carcinoma (7 papers, 2016 to 2023). "TRPV3 oncogenic activity was demonstrated in lung cancer, where TRPV3 expression was associated with short overall survival and Ca2+-mediated increased proliferation via Ca2+/calmodulin-dependent kinase II (CaMKII)." (PMID 35806388, 2022). "Statistically, TRPV3 expression is decreased in colorectal cancer, and it is increased in pancreatic cancer, bone cancer, breast cancer, lung cancer and oral squamous cell carcinoma." (PMID 36677834, 2023). "In non-small cell lung carcinoma, the inhibition of TRPV3 led to the reduction in Ca2+ ions that arrested the lung cancer cells at the G1/S stage; reduced the expression of cyclinA, cyclinD1, cyclinE, and p-CaMKII; and increased the P27 level." (PMID 37529379, 2023). "Currently, only a few channels of the TRP family have been characterized as having a role in tumor angiogenesis, such as TRPV4, TRPV3, TRPM3, and TRPA1, demonstrated in lung carcinoma, renal cell carcinoma, cancer-associated fibroblast, and prostate cancers." (PMID 37576552, 2023). "Overexpression of TRPV3 in human lung cancer cells correlates with a poor overall survival of lung cancer patients, but blocking TRPV3 efficiently inhibits the proliferation of lung cancer cells." (PMID 33921049, 2021). "From fluorescence intensity taken by laser scanning confocal microscope, we found that blocking or knockdown of TRPV3 remarkably decreased [Ca2+]i of lung cancer cells." (PMID 27023518, 2016). "To validate the potential role of TRPV3 in lung cancer development, we employed TRPV channel blocker RuR and siRNA to inhibit or knockdown TRPV3 expression in A549 and H1299 cell lines." (PMID 27023518, 2016). "We utilized an independent method, colony formation assays, to validate the anti-proliferative effect of TRPV3 inhibition in lung cancer cells." (PMID 27023518, 2016). "Together, these results suggested that inhibiting TRPV3 expression induced cell cycle arrest at the G1-S transition and suppressed A549 and H1299 lung cancer cell growth." (PMID 27023518, 2016). "In order to explore the biological function of TRPV3 in lung cancer, we used ruthenium red (RuR, a broad spectrum calcium channel blocker) and siRNA techniques to block and knockdown TRPV3 expression in A549 and H1299 cell lines." (PMID 27023518, 2016). "TRPV3 inhibition decreased [Ca2+]i of lung cancer cells and cell cycle arrest at the G1/S boundary." (PMID 27023518, 2016). "Our data suggested that high TRPV3 protein expression could promote the proliferation of A549 and H1299 lung cancer cells." (PMID 27023518, 2016). "However, the mechanism of TRPV3 on proliferation of lung cancer cells should be addressed in future studies." (PMID 27023518, 2016). "Moreover, the effect of TRPV3 on the proliferation ability of lung cancer cells was also investigated." (PMID 27023518, 2016). "TRPV3 blocking or knockdown inhibited G1 to S transition in cell cycle progression, which might explain the mechanism of TRPV3 on lung cancer cell proliferation." (PMID 27023518, 2016). "Importantly, the inhibition of TRPV3 slowed the proliferation of lung cancer cells." (PMID 36677834, 2023). "TRPV3 activation could promote proliferation of lung cancer cells." (PMID 27023518, 2016). "In addition, the biological roles of TRPV3 in lung cancer cells are still unclear." (PMID 27023518, 2016). "High TRPV3 protein expression could promote the proliferation of lung cancer cells." (PMID 27023518, 2016). "Moreover, TRPV3 inhibition could decrease [Ca2+]i of lung cancer cells and arrest cell cycle at the G1/S boundary." (PMID 27023518, 2016). "In addition, blocking or knockdown of TRPV3 could inhibit lung cancer cell proliferation." (PMID 27023518, 2016). "TRPV3 is a member of the TRP family and we found that blocking or knockdown TRPV3 remarkably decreased [Ca2+]i of A549 and H1299 lung cancer cells by laser scanning confocal microscope." (PMID 27023518, 2016).
Palmoplantar keratoderma (7 papers, 2018 to 2025). Abnormal thickening of the skin of the palms of the hands and the soles of the feet. "TRPV3 regulated by mutated MBTPS2 or directly mutated TRPV3 might function in a dominant‐positive manner to increase constitutive TRPV3 activity and elevate Ca2+ in keratinocytes, leading to severe keratoderma." (PMID 35342611, 2022). "For example, a mutation of TRPV3 or membrane‐bound transcription factor protease site 2 (MBTPS2) could lead to Olmsted syndrome, described by bilateral mutilating palmoplantar keratoderma (PPK) and periorificial keratotic plaques." (PMID 35342611, 2022).
colorectal cancer (6 papers, 2011 to 2023). A primary or metastatic malignant neoplasm that affects the colon or rectum. "The association between 43 fatty acid metabolism genes and genetic variability in colorectal cancer indicated TRPV3 with four fatty acid metabolism genes to be associated with a higher risk of colorectal tumor progression." (PMID 37529379, 2023). "Previous reports indicated that the proliferation rate in the oral epithelia of TRPV3 knockout mice was less than that of wild-type mice, and TRPV3 upregulation was also shown to be associated with a high risk for development of colorectal cancer." (PMID 27023518, 2016). "TRPV3 was also shown to be associated with a higher risk of colorectal cancer." (PMID 36677834, 2023). "With the exception of one study reporting its association with a higher risk of colorectal cancer, none others have investigated the role of TRPV3 in gut disease." (PMID 32823895, 2020). "It would be interesting to define the role of endothelial TRPV channels in angiogenesis and carcinogenesis as recent published data implies that TRPV3, TRPV4, TRPV5, TRPM4 and TRPC6 may be thought of as potential genes contributing to colorectal cancer tumorigenesis." (PMID 29914124, 2018).
Hyperkeratosis (6 papers, 2021 to 2024). Hyperkeratosis is a histopathological term defining a thickened stratum corneum and may be present in many different skin conditions, with many possible overlaps. "Gain-of-function mutations in TRPV3 alter channel properties leading to enhanced keratinocyte apoptosis, hyperkeratosis, and increased epidermal turnover." (PMID 39469632, 2024). "Gain-of-function mutations in TRPV3 in mice and humans are characterized by severe itching, hyperkeratosis, and elevated total IgE levels." (PMID 36499288, 2022). "The pathogenesis of OS remains unclear, but it is hypothesized that TRPV3 gain-of-function mutations lead to increased intracellular calcium levels, inducing keratinocyte apoptosis, and contributing to the characteristic hyperkeratosis of OS." (PMID 39469632, 2024). "Conversely, gain-of-function mutations of TRPV3 lead to mutilating hyperkeratosis in humans." (PMID 35098357, 2022). "The atypical activity of TRPV3 channels leads to greater epidermal thickness in the layer of stratum corneum (hyperkeratosis), granular layer (hypergranulosis), stratum spinosum, and stratum basale, consistent with previous studies." (PMID 35058747, 2021). "Despite progress, it remains uncertain why a gain of function of TRPV3 leads to hyperkeratosis in humans." (PMID 34664138, 2021).
cardiac hypertrophy (5 papers, 2018 to 2023). "TRPV3 protein, cardiac hypertrophy marker proteins (BNP and β‐MHC) and autophagy associated proteins (Beclin‐1 and LC3‐II) were up‐regulated, as well as, miR‐103 expression and autophagy associated proteins (p62) were down‐regulated in cardiac hypertrophy models in vivo and in vitro respectively." (PMID 30604587, 2019). "The current studies have revealed that TRPV3 plays a regulatory role in temperature perception, pain transduction, skin physiology, inflammation, cancer and cardiac hypertrophy." (PMID 36677834, 2023). "Further studies have showed that TRPV3 activation aggravated pathological cardiac hypertrophy through calcineurin/NFATc3 signaling." (PMID 36677834, 2023). "TRPV3 was elevated in pathological cardiac hypertrophy, and TRPV3 expression was also increased in Ang II-induced cardiomyocyte hypertrophy in vitro." (PMID 36677834, 2023). "According to our previous study, TRPV3 aggravates pathological myocardial hypertrophy through the calcineurin/NFATc3 pathway, promoting the extracellular Ca2+ flow and increases [Ca2+]i, and aggravates cardiac fibrosis through the TGF-β1 pathway." (PMID 33470394, 2021). "The third study by Sun’s laboratory sought to determine the role of miR-103 in cardiac hypertrophy, especially as it pertains to the activation of TRPV3." (PMID 34867442, 2021). "TRPV3 activation exacerbates cardiac fibrosis by promoting cardiac fibroblast proliferation and exacerbating pathological myocardial hypertrophy." (PMID 33470394, 2021). "In 2018, TRPV3 expression was confirmed in the heart and recent reports suggest potential roles for TRPV3 in cardiac hypertrophy and fibrosis." (PMID 34867442, 2021). "Together, these findings indicated that activating TRPV3 channel promoted the occurrence of cardiac hypertrophy." (PMID 30604587, 2019). "To further confirm the regulation of TRPV3 on cardiac hypertrophy, we used siRNA technology to silence TRPV3." (PMID 30604587, 2019). "The main findings of the current study are that miR‐103 exerts the inhibitory effect on cardiac hypertrophy partly via reducing cardiac autophagy by directly targeting TRPV3." (PMID 30604587, 2019). "Secondly, to further evaluate the role of TRPV3 in cardiac hypertrophy, we used siRNA to target TRPV3, and suppressed the expression of TRPV3 successfully." (PMID 30604587, 2019). "The main purpose of the present study was to confirm the following problems: Are miR‐103, TRPV3 and autophagy related to the occurrence of cardiac hypertrophy?" (PMID 30604587, 2019). "To identify the specificity of TRPV3 increase in pathological cardiac hypertrophy, we used the swimming training protocol to establish physiological cardiac hypertrophy." (PMID 30299584, 2018). "Taken together, our results supported this idea that calcineurin/NFATc3 pathway was involved in the cardiac hypertrophy induced by the activation of TRPV3." (PMID 30299584, 2018). "In this study, to our knowledge, we demonstrated, for the first time, that the expression of TRPV3 was increased in pathological cardiac hypertrophy." (PMID 30299584, 2018). "We found that TRPV3 activation promoted cardiac hypertrophy via Ca2+/CaMKII/calcineurin/NFATc3 pathway." (PMID 30299584, 2018). "A series of results have suggested that TRPV3 may be a potential therapeutic target for myocardial hypertrophy." (PMID 36677834, 2023). "Therefore, they concluded that activation of TRPV3 leads to an increase in intracellular Ca2+ concentration, which in turn activates calcineurin and NFATc3 to induce cardiac hypertrophy." (PMID 34867442, 2021). "TRPV3 siRNA reduces relative fluorescence intensity of Ca2+ signal, leading to the decrease in the activation of cardiac autophagy and ultimately inhibiting the development of cardiac hypertrophy." (PMID 33470394, 2021).